PTH (parathyroid hormone)
Diseases named in the same sentence as PTH in open-access papers (continued):
Sharing a sentence is not in itself a finding about the gene and the disease.
hypoparathyroidism (continued). "Hypoparathyroidism (HP) is an endocrine disorder characterized by the hyposecretion of parathyroid hormone (PTH), with a prevalence of less than 3 cases per 10,000 individuals." (PMID 40726585, 2025). "Of the two patients with low PTH at the first follow-up (both in the PA subgroup), only one was diagnosed with persistent hypoparathyroidism at 6 months after surgery (1.2% of the entire cohort of patients)." (PMID 40507262, 2025). "Using the first method, based on the occurrence of postoperative hypoparathyroidism, 364 patients (47.4%) remained within the normal postoperative serum PTH range, while 404 (52.6%) developed hypoparathyroidism." (PMID 40969367, 2025). "Short-term follow-up: The 30-day observation period prevents assessment of permanent hypoparathyroidism (defined as PTH <15 pg/mL at 6 months), leaving the long-term protective effects of papaverine uncertain." (PMID 41356014, 2025). "Compared with hypoparathyroidism cases presenting as neonatal seizures, cases with PTH resistance often initially present with short stature." (PMID 41155848, 2025). "Assess the long-term efficacy and safety of TransCon PTH (palopegteriparatide) for hypoparathyroidism." (PMID 39376010, 2025). "Hypoparathyroidism can be successfully treated with activatedvitamin D analogues and calcium supplements as the primary therapy, or replacement therapy with PTH or PTHanalogues in selected cases." (PMID 40838538, 2025). "Hypoparathyroidism (HypoPT) is an endocrine disorder defined as inadequately low or undetectable parathyroid hormone (PTH) secretion from the parathyroid glands accompanied by low concentrations of corrected total calcium or ionized calcium in serum." (PMID 40178746, 2025). "Depletion of PTH due to hypoparathyroidism, such as in the case of incidental removal during surgery, can lead to severe, long-term outcomes for patients including osteoporosis and neurological dysfunction." (PMID 40225464, 2025). "Indices of skeletal dynamics through week 52 of the PaTHway trial suggest that TransCon PTH augments the turnover of bone in a low turnover state and mobilizes calcium from the abnormally dense skeleton of adults with hypoparathyroidism." (PMID 39376010, 2025). "Tracking transient versus permanent hypoparathyroidism requires extended monitoring and multiple biochemical data points (for example PTH and calcium levels), which are often missing or inconsistently recorded in quality registries." (PMID 41229353, 2025). "The mean age of hypoparathyroid patients was 62.68 ± 8.07 years and, as expected, serum calcium and PTH levels were significantly lower compared to controls, while phosphorus was higher (all p < 0.05)." (PMID 40346324, 2025). "At week 52 of the PaTHway trial, TransCon PTH showed sustained efficacy, safety, and tolerability in adults with hypoparathyroidism." (PMID 39376010, 2025). "For individuals with hypoparathyroidism, there remains an unmet need for a PTH therapy capable of providing physiological levels of PTH, reducing symptom burden and long-term complications, and improving HRQoL." (PMID 39376010, 2025). "Several pathologies can be responsible for the dysregulation of PTH–either being too high or too low–referred to as hyperparathyroidism or hypoparathyroidism, respectively." (PMID 40740723, 2025). "With our data, we hope to provide some assistance to colleagues in other countries, in which TransCon PTH has also received approval from the respective authorities and will be available to treat their hypoparathyroidism patients." (PMID 40709359, 2025). "The patient experienced transient hypoparathyroidism, after which sheremained asymptomatic, with normal PTH and calcium levels." (PMID 40893023, 2025). "This patient was persistently hypocalcemic throughout the hospital stay, which, in conjunction with low parathyroid hormone levels and upper limit of normal phosphorus levels, indicated some degree of hypoparathyroidism." (PMID 41018325, 2025).
hypoparathyroidism (continued). "As expected, serum calcium and PTH levels were significantly lower in hypoparathyroid patients compared to controls, while phosphorus was higher (all p < 0.05)." (PMID 40346324, 2025). "Long-term treatment with TransCon PTH through week 52 of the phase 3 PaTHway trial showed a durable and favorable efficacy, safety, and tolerability profile in adults with hypoparathyroidism." (PMID 39376010, 2025). "Higher sunshine levels correlate with higher preoperative serum ionized calcium and postoperative parathyroid hormone levels, leading to a lower incidence of postoperative hypoparathyroidism after thyroid surgery." (PMID 40648792, 2025). "The role of preoperative levels of calcium and pre- and postoperative parathyroid hormone levels in predicting hypoparathyroidism is already established." (PMID 40648792, 2025). "Postsurgical hypoparathyroidism (PH) is a common complication following thyroidectomy and parathyroidectomy which results in decreased circulating PTH and subsequent hypocalcemia and hyperphosphatemia." (PMID 40225464, 2025). "In contrast, hypoparathyroidism is characterized by chronically low PTH levels, most often due to neck surgery (up to 75%–80% of cases), but also from autoimmune causes, genetic syndromes, or infiltrative diseases." (PMID 41211056, 2025). "Treatment of hypoparathyroidism with TransCon PTH in long-term phase 2 and 3 clinical trials demonstrates a consistent and sustained trend toward a new skeletal steady state closer to age-appropriate norms." (PMID 39376010, 2025). "The phase 3 PaTHway trial of TransCon PTH in adults with chronic hypoparathyroidism met the primary and all key secondary endpoints with statistically significant differences from placebo." (PMID 39376010, 2025). "All patients were discharged within 1–3 days, with normalized calcium and parathyroid hormone levels, except for one case of permanent hypoparathyroidism due to previous total parathyroidectomy." (PMID 40364052, 2025). "In our patient, undetectable serum PTH and several episodes of tetany confirmed the patient’s history of iatrogenic hypoparathyroidism." (PMID 39851484, 2025). "The incidence of hypoparathyroidism on postoperative day 1 and the PTH recovery rate within 30 days afterward are compared between patients who received papaverine and those who did not." (PMID 41356014, 2025). "On POD1, 62 out of 135 DTC patients (45.93%) developed hypoparathyroidism, with an average PTH level of 20.86 ± 16.05 pg/mL, an average serum calcium level of 1.99 ± 0.15 mmol/L, and an average serum phosphorus level of 1.5 ± 0.31 mmol/L." (PMID 40066709, 2025). "Of the two patients with low PTH at the first follow-up (both belonging to the PA subgroup), only one was diagnosed with persistent hypoparathyroidism at 6 months after surgery." (PMID 40507262, 2025). "Patients were stratified into hypoparathyroidism and euparathyroidism groups based on the parathyroid hormone levels measured on the first postoperative day." (PMID 40426871, 2025). "The incidence of postoperative hypoparathyroidism is significantly higher among patients who underwent total thyroidectomy and had a normal level of preoperative PTH and Mg levels." (PMID 38646308, 2024). "Activation of CaSR in the parathyroid gland leads to inhibition of parathyroid hormone (PTH) release and subsequent hypoparathyroidism." (PMID 38606357, 2024). "In contrast, permanent hypoparathyroidism persists beyond six months post-surgery, necessitating lifelong supplementation and potentially PTH replacement therapy." (PMID 39258042, 2024). "Management of transient hypoparathyroidism usually involves calcium and vitamin D supplementation during the recovery period, with most patients eventually returning to normal PTH levels and calcium homeostasis." (PMID 39258042, 2024). "Even in patients later unaffected by hypoparathyroidism,parathyroid hormone levels drop within hours after surgery." (PMID 39022353, 2024).
hypoparathyroidism (continued). "Calcium and phosphate serum levels were normal in all patients, except for a patient with postsurgical hypoparathyroidism, due to papillary thyroid carcinoma, also the only one with low PTH." (PMID 38633760, 2024). "In a recent multicentre cohort study, a drop in PTH on the first postoperative day compared with the preoperative value was a reliable predictor of hypoparathyroidism." (PMID 38478048, 2024). "The remaining 3 of the 42 patients with definitive permanent hypoparathyroidism had an immediate PTH level that was within the normal reference range, albeit just above the lower limit (PTH less than 5 per cent above lower reference limit)." (PMID 37995259, 2024). "Secondly, the gender different levels in PTH and vitamin D can affect postoperative parathyroid function recovery: moreover, thyroid surgery may disrupt hormone balance, particularly in menopause women, thereby increasing the risk of postoperative hypoparathyroidism." (PMID 39457684, 2024). "According to a previous study, the incidence of permanent hypoparathyroidism, defined as PTH < 10 pg/mL at 1‐year postthyroidectomy, was 1.9%." (PMID 38371915, 2024). "Teriparatide (PTH 1-34), the most widely available form of PTH, has been used to treat children with various etiologies of hypoparathyroidism through daily or bi-daily subcutaneous injections." (PMID 39246904, 2024). "Hypoparathyroidism is a rare endocrine disorder characterized by low blood calcium levels, elevated phosphorus levels, and insufficient parathyroid hormone production." (PMID 38186939, 2024). "One-quarter of all patients with an early low PTH level below the reference range develop permanent hypoparathyroidism." (PMID 37995259, 2024). "Hypomagnesaemia was shown to inhibit the release of PTH and potentially reduce sensitivity to PTH signaling in target organs, thus mimicking hypoparathyroidism." (PMID 39717475, 2024). "Among those who received TransCon PTH, all 15 respondents (100%) indicated that they preferred the trial treatment compared to their previous hypoparathyroidism treatment:I prefer the trial treatment." (PMID 39136801, 2024). "Once PTH came back as low, the endocrine team revised their diagnosis to postoperative hypoparathyroidism." (PMID 39328612, 2024). "Among those in the TransCon PTH group, 14 participants (93.3%) reported a reduced frequency of their overall hypoparathyroidism symptoms from the pre-trial period to the past 2 weeks on the PGIS." (PMID 39136801, 2024). "Patients with permanent hypoparathyroidism require lifelong calcium and vitamin D supplementation and, in some cases, PTH replacement therapy." (PMID 39258042, 2024). "Approximately one-quarter of all patients with low PTH levels immediately after surgery developed permanent hypoparathyroidism." (PMID 37995259, 2024). "A proportion of 23.2 per cent with a PTH level below the reference value corresponded to a 6.7 per cent rate of permanent hypoparathyroidism." (PMID 37995259, 2024). "The aim of this study was to evaluate drop in PTH as a predictor for PoSH and compare it with postoperative PTH alone in the detection of postsurgical hypoparathyroidism." (PMID 38478048, 2024). "Hypoparathyroidism is a common complication following thyroidectomy, resulting in significant disturbances in calcium homeostasis due to low parathyroid hormone (PTH) levels." (PMID 39258042, 2024). "In this case, either permanent hypoparathyroidism with inadequate calcium intake or an artificial suppression of the PTH value due to a continued superfluous intake of calcium supplements were plausible explanations for the result." (PMID 39636417, 2024). "Hypoparathyroidism was treated with oral alfacalcidol (0.5–1 mcg/day), with dose titration based on calcium and PTH levels." (PMID 39797201, 2024).
hypoparathyroidism (continued). "Findings indicate that TransCon PTH treatment improved participants’ physical and cognitive hypoparathyroidism symptoms in meaningful ways, while reducing the daily burden associated with conventional therapy." (PMID 39136801, 2024). "A strict definition of definitive permanent hypoparathyroidism was used, including data on both PTH and calcium values, as well as documented attempts to stop the treatment, making the diagnosis of permanent hypoparathyroidism highly reliable." (PMID 37995259, 2024). "Postoperative monitoring of calcium and PTH levels is vital for the early detection of hypoparathyroidism." (PMID 39258042, 2024). "Relative hypoparathyroidism is a term used when the levels of PTH are normal but insufficient to keep calcium within normal limits." (PMID 37995259, 2024). "Supporting hypoparathyroidism, she had low levels of serum parathyroid hormone, calcium, and vitamin D and a high level of serum phosphorus." (PMID 38510220, 2024). "Participants in the TransCon PTH group reported marked improvement in overall, physical, and cognitive hypoparathyroidism symptoms, while those in the placebo group reported limited or no improvement." (PMID 39136801, 2024). "In contrast, patients with hypoparathyroidism would exhibit lower-than-normal PTH levels, along with high normal or elevated phosphate levels." (PMID 39328612, 2024). "All 15 participants (100%) in the TransCon PTH group confirmed that reduced frequency of their hypoparathyroidism physical symptoms made a difference that mattered to how they feel or function." (PMID 39136801, 2024). "Mean serum PTH values on the day of surgery were 3.07 ± 3.03 pmol/L, with 49 patients (23.9%) having hypoparathyroidism." (PMID 38322433, 2024). "This case also reported to have very low parathyroid hormone levels, with evidence of basal ganglia calcifications, which favors a diagnosis of primary hypoparathyroidism." (PMID 38600559, 2024). "The interview findings have shown that trial participants who received TransCon PTH were generally satisfied with the treatment and found it to be effective or very effective for their hypoparathyroidism symptom management." (PMID 39136801, 2024). "Surprisingly, the prevalence of postoperative hypoparathyroidism was significantly higher among patients who had a normal level of preoperative PTH and Mg levels." (PMID 38646308, 2024). "A secondary aim was to assess the relationship between the rate of low parathyroid hormone (PTH) levels within 24 h after surgery and the rate of permanent hypoparathyroidism." (PMID 37995259, 2024). "Respondents who received TransCon PTH unanimously preferred the trial treatment to their previous hypoparathyroidism treatment, primarily due to its efficacy/symptom improvement and the frequency of administration/single daily dose." (PMID 39136801, 2024). "Validated outcome measures were used to evaluate the impact of TransCon PTH on a wide range of clinical aspects of hypoparathyroidism, as well as HRQoL and disease‐specific functioning and well‐being." (PMID 36271471, 2023). "For patients with postoperative hypoparathyroidism, PTH within three days after surgery cannot be measured had predictive significance for the occurrence of permanent hypoparathyroidism." (PMID 37545843, 2023). "Total PTx without transcervical thymectomy and autograft is performed to prevent hypoparathyroidism after PTx as PTH secretion is expected from the ectopic and supernumerary PTGs in the thymus." (PMID 37152972, 2023). "The double‐blind, placebo‐controlled, 26‐week, phase 3 PaTHway trial assessed the efficacy and safety of PTH replacement therapy for hypoparathyroidism individuals with the investigational drug TransCon PTH (palopegteriparatide)." (PMID 36271471, 2023).
hypoparathyroidism (continued). "These included serum phosphorus levels on postoperative day 1 (P = 0.028), serum intact PTH levels on postoperative day 1 (P = 0.012), incidence of hypoparathyroidism after initial PTx (P < 0.001), and observation period (P = 0.003)." (PMID 37396185, 2023). "Concerning patients with temporary hypoparathyroidism, they were found to have lower preoperative PTH (439.0 ± 12.7 vs 778.1 ± 693.4; p=0.013)." (PMID 38027172, 2023). "After laboratory examinations, hypoparathyroidism was diagnosed based on low serum calcium, elevated serum phosphorous, and lower serum intact parathyroid hormone (PTH) levels." (PMID 37213970, 2023). "Persistent hypoparathyroidism or altered response to PTH (pseudohypoparathyroidism) leads to low blood calcium levels and high phosphate, thus promoting calcium phosphate crystals deposition." (PMID 36862146, 2023). "Few cases of transient hypoparathyroidism evolve into permanent hypoparathyroidism, bilateral CND, lymphatic metastasis, and PTH within three days after surgery <1.2 pg/ml were the risk factors for postoperative permanent hypoparathyroidism." (PMID 37545843, 2023). "Third, biochemical hallmarks of hypoparathyroidism improved upon ruxolinitib treatment, suggesting an increase in PTH secretion." (PMID 38112858, 2023). "In conclusion, TransCon PTH maintained normocalcemia while permitting independence from conventional therapy and was well‐tolerated in individuals with hypoparathyroidism." (PMID 36271471, 2023). "When comparing patients with transient and permanent hypoparathyroidism, we added the variable PTH within three days after surgery <1.2 pg/ml." (PMID 37545843, 2023). "The sensitivity and specificity for a low level of PTH to predict postoperative treatment of hypoparathyroidism at any time after surgery was 66.2 and 88.8 per cent respectively." (PMID 37758507, 2023). "At present, many studies have predicted postoperative hypoparathyroidism and recovery by measuring the results of PTH or serum ions at different time points." (PMID 37091845, 2023). "Despite this, the normal thymus tissue must be properly preserved to prevent permanent hypoparathyroidism as it is a potential source of PTH after tPTX." (PMID 36331700, 2023). "Transient hypoparathyroidism was defined as a decrease in serum PTH below 15 pg/mL, and permanent hypoparathyroidism was defined as a decrease in the serum PTH below 15 pg/mL with the need for oral calcium supplementation for longer than 1 year." (PMID 37296896, 2023). "The treatment of hypoparathyroidism with human parathyroid hormone (hPTH) or recombinant human parathyroid hormone (rhPTH) increases bone turnover, while bone mineral density shows increases at the hip and spine level and decreases at the radiocarpal level." (PMID 37653972, 2023). "Hypoparathyroidism, a condition marked by the insufficient production of parathyroid hormone, can lead to a range of complications, and this innovative approach offers a new avenue for treatment." (PMID 38247755, 2023). "Univariate analysis showed that patients with bilateral CND (P = 0.049) and PTH within three days after surgery <1.2 pg/ml (P = 0.006) were more likely to develop permanent hypoparathyroidism." (PMID 37545843, 2023). "Permanent hypoparathyroidism was determined as PTH < 10 pg/mL with constant low PTH levels throughout the follow-up period." (PMID 37716097, 2023). "Existing genetically modified animal models of hypoparathyroidism include mice carrying parathyroid hormone (PTH)-null or Glial Cells Missing Homolog 2 (GCM2)-null alleles." (PMID 37180074, 2023). "The main risk factors associated with permanent hypoparathyroidism were bilateral CND (P = 0.038), lymphatic metastasis (P = 0.047), parathyroid hormone (PTH) < 1.2 pg/ml within three days after surgery (P = 0.006)." (PMID 37545843, 2023).